TIMP1 (TIMP metallopeptidase inhibitor 1)
Diseases named in the same sentence as TIMP1 in open-access papers (continued):
Sharing a sentence is not in itself a finding about the gene and the disease.
colon carcinoma (84 papers, 2004 to 2026). "A recent paper shows that upregulated TIMP1 is associated with both proliferation and invasive capacity in colon cancer." (PMID 41002380, 2025). "Previous studies have found that TIMP1 is associated with primary sarcopenia, colon cancer progression and metastasis, and some infectious diseases." (PMID 35720085, 2022). "Paradoxically, however, recent studies have shown that high levels of TIMP-1 in both plasma and tumor tissue are associated with poor prognosis in several cancers, including prostate and colon cancer." (PMID 33708191, 2020). "In another, with 97 colon cancer patients, high TIMP-1 associated with shorter overall survival and emerged as an independent prognostic factor." (PMID 29929486, 2018). "We also sought to determine the role of TIMP1 in colon cancer cell biological function and the underlying molecular mechanisms." (PMID 27644693, 2016). "In human colon cancer cells, TIMP-1 conferred resistance against cytotoxicity caused by TNF-α and IL-2, and contributed to clonogenicity and tumor growth during early tumor formation." (PMID 24518611, 2014). "Increased levels of TIMP-1 were observed in patients with colon cancer, which also was associated with a worse outcome." (PMID 24518611, 2014). "Results from several recent clinical studies have demonstrated that TIMP-1 levels in cancer patient plasma are elevated and the elevated TIMP-1 levels are associated with worse clinical outcomes in many cancer types including prostate and colon cancer." (PMID 24143225, 2013). "We also show that increased expression of TIMP-1 stimulates accumulation of cancer associated fibroblasts (CAFs) within prostate/colon cancer tissues." (PMID 24143225, 2013). "For example, TIMP1, as a matrix metalloproteinase inhibitor, can promote tumor invasion and angiogenesis by inhibiting matrix degradation, and its high expression is associated with poor prognosis in colon cancer." (PMID 41523911, 2026). "In human colon cancer, overexpressed of TIMP1 associated with worse OS." (PMID 34093812, 2021). "However, the precise function and underlying mechanisms of TIMP1 remain to be elucidated in colon cancer." (PMID 27644693, 2016). "Recently, several clinical studies have demonstrated that TIMP-1 levels in cancer patient plasma and cancer tissues are highly elevated and the elevated TIMP-1 levels are associated with worse clinical outcomes in many cancer types including prostate and colon cancer." (PMID 24143225, 2013). "In this work, we performed RNA‐seq and observed that FN1 and TIMP1 were the most upregulated genes between metastasis and primary colon cancer tissues as well as between primary colon cancer tissues and adjacent normal tissues." (PMID 40638546, 2025). "The ferroptosis-related gene TIMP1 has been observed to regulate PD-L1, thereby promoting anti-tumor immunity in colon cancer." (PMID 40290432, 2025). "Literature reports that SPI1 interacts with IRF1 or TIMP1 to regulate the sensitivity of colon cancer to ferroptosis." (PMID 41372608, 2025). "Previous research has highlighted the importance of TIMP1 in the progression and metastasis of colon cancer, particularly through the FAK-PI3K/AKT and MAPK pathways." (PMID 40777024, 2025). "Down-regulation of TIMP1 inhibited the proliferation and metastasis of colon cancer, but promoted apoptosis through the focal adhesion PI3K/AKT and mitogen-activated protein kinase pathway." (PMID 39177661, 2024). "TIMP1 is regarded as a novel predictive biomarker for colon cancer due to its close relationships to processes and functions pertaining to the metastasis, proliferation, and apoptosis of cancer cells." (PMID 38742936, 2024). "According to a previous report, TIMP1 serves as a prognostic marker for colon cancer development and metastasis via the MAPK and AKT-pi3k/AKT pathways." (PMID 38307957, 2024).
colon carcinoma (continued). "To validate our data analysis results, we extracted total RNA from patient colon cancer tissue and corresponding normal colon epithelial tissue and measured the mRNA expression levels of TIMP1, VEGFA, MYC, MSLN, EPHA2, ABHD2, and CD24." (PMID 38773226, 2024). "TIMP1 is also thought to be a viable target for the treatment of colon cancer since it was shown that it stimulates the growth and invasiveness of right-sided colon cancer cells via the FAK/Akt signaling pathway." (PMID 38742936, 2024). "In colon cancer, TIMP1 induces cell proliferation and invasion through the FAK/Akt signaling pathway." (PMID 37542061, 2023). "The knockdown of TIMP1 expression inhibited metastasis, and proliferation but prompted apoptosis of colon cancer through activating FAK-PI3K/AKT and MAPK pathway." (PMID 37056778, 2023). "Together, these results demonstrate the significance of CCL3, MMP3, and TIMP1 in recruiting and regulating infiltrating immune cells in colon cancer." (PMID 36742294, 2023). "Conversely, TIMP1 is overexpressed in colon cancer and leads to tumor proliferation, metastasis and apoptosis inhibition via the FAK-PI3K/AKT and MAPK pathways." (PMID 37014331, 2023). "This is in agreement with previously published data showing that LoVo colon cancer cells produce an order of a magnitude less TIMP-1 than CAFs." (PMID 36291767, 2022). "For instance, TIMP-1 was already shown to promote tumor progression in prostate and colon cancer models, by driving the accumulation of CAFs." (PMID 35805073, 2022). "For instance, in colon cancer, TIMP-1-expressing CAFs are frequently present in those cancers associated with Crohn’s disease, a chronic inflammatory, IL-6-dependent disease." (PMID 36291767, 2022). "Studies have shown that TIMP1 can inhibit apoptosis and promote colon cancer occurrence and metastasis through FAK-PI3K/AKT and MAPK pathways." (PMID 36439446, 2022). "In another study, CAF-derived TIMP-1 promoted the migration of a colon cancer cell line, whereas TIMP-1 neutralization inhibited the enhanced migration, and TIMP-1 secretion was higher in CAFs co-cultured with cancer cells than in monocultured CAFs." (PMID 36555218, 2022). "Overall, we hope these drugs will bind to TIMP1, relieving the progression of colon cancer and the occurrence of drug resistance." (PMID 36146640, 2022). "TIMP-1 has been proposed as a potential prognostic biomarker in several solid cancers, including breast and colon cancer." (PMID 36457117, 2022). "Given that TIMP1 promotes tumorigenesis and metastasis of human colon cancer, it is a potential prognostic biomarker for the cancer." (PMID 34907282, 2021). "Results showed increased expression levels of the MYC/CXCL8/TIMP1 oncogenes across colon cancer cell lines." (PMID 34440739, 2021). "The box plots suggested that the ITLN1, TSPAN11, CPRC5B, and CXCL13 genes were significantly lowly expressed in the colon cancer samples and the TIMP1 gene was highly expressed in the colon cancer samples in the TCGA cohort." (PMID 33579281, 2021). "Four prognostic hub genes associated with M2 macrophages in colon cancer were identified as follows: ANK4B, CTSD, TIMP1, and ZNF703, and the stability of these results was verified by different clustering methods and GSE39582 dataset." (PMID 34552622, 2021). "Moreover, knockdown of TIMP1 could promote apoptosis of colon cancer cells via BCL2-Associated Agonist Of Cell Death (BAD) mediated phosphoration pathway and suppress the migration and invasion of cancer cells through downregulating Fibronectin and upregulating E-cadherin." (PMID 34670584, 2021). "Five genes (FAS, VWA5A, SPTBN2, PCK1, and TIMP1) significantly affect the prognosis of patients with colon cancer." (PMID 34957118, 2021). "Tissue inhibitor matrix metalloproteinase 1 (TIMP1) has been reported to act as a tumor oncogene in colon cancer." (PMID 34775375, 2021).
colon carcinoma (continued). "TIMP1 was also reported to participate in various cell functions including proliferation and survival, leading to reduced sensitivity to chemotherapy in colon cancer." (PMID 34440739, 2021). "Studies have shown that TIMP1 is highly expressed in colon cancer and leads to tumor proliferation, metastasis, and anti-apoptosis through the FAK-PI3K/AKT and MAPK pathways." (PMID 34957118, 2021). "TIMP1 expression in colon cancer tissues was greater than that in normal tissues, and the expression was located in the cytoplasm and cell membrane, which was consistent with the expression trends of the GEO and TCGA cohorts." (PMID 33579281, 2021). "Although BMDMs expressed TIMP-1 in an MK2-dependent manner, we found that MK2 whole-body knock-out mice showed similar TIMP-1 levels within inflammatory colon tumors, suggesting more complex regulation of TIMP-1 in an in vivo setting." (PMID 33708191, 2020). "In human colon cancer cells, it was shown that TIMP1 positively regulates proliferation and renders tumor cells more resistant to apoptosis through the activation of FAK-PI3K/AKT and the MAPK signaling pathway." (PMID 28430130, 2017). "This suggests that TIMP1 is of clinical significance in the diagnosis and prognosis of patients with colon carcinomas." (PMID 27644693, 2016). "In the present study, we investigate the expression of TIMP1 at the mRNA and protein level in human colon cancer and clarify the correlation between the TIMP1 expression and clinicopathological parameters." (PMID 27644693, 2016). "We analyzed the expression of TIMP1 in both public database (Oncomine and TCGA) and 94 cases of primary colon cancer and matched normal colon tissue specimens." (PMID 27644693, 2016). "Serum TIMP-1 has been reported to be elevated in breast, gastric, colon cancer and several other cancer types." (PMID 24143225, 2013). "Recently, Kim and coworkers showed that colon cancer cells have TIMP1 molecule bearing aberrant glycosylation, which impairs its efficient function as MMP inhibitor." (PMID 23522389, 2013). "Accumulation of CAFs induced by TIMP-1 within prostate and colon cancers can be achieved through stimulating CAF infiltration, expansion/proliferation, and/or trans-differentiation of the resident fibroblasts to CAFs." (PMID 24143225, 2013). "To further validate the general pro-tumor activity of TIMP-1 and its general effect on CAFs, we assess TIMP-1 levels in colon cancer and normal colon samples." (PMID 24143225, 2013). "Increased β1, 6 branching of N-glycans of TIMP-1, induced by GnT-V N-acetylglucosaminyltransferase, was closely correlated with invasive/metastatic potential of colon cancer cell WiDr." (PMID 24015777, 2013). "Here, we showed that cancer stroma expresses higher levels of TIMP-1 compared to their normal counterparts and that increased expression of TIMP-1 promotes accumulation of CAFs within prostate/colon cancer tissues." (PMID 24143225, 2013). "In this study, we establish that increased expression of TIMP-1 promotes in vivo growth of prostate cancer and colon cancer." (PMID 24143225, 2013). "Interestingly, CREB was also involved in the induction of FN1 and TIMP1 expression, thereby leading to a positive feedback loop in colon cancer metastasis." (PMID 40638546, 2025). "TIMP1 predicts colon cancer progression and metastasis through the FAK-PI3K/AKT and MAPK pathways." (PMID 40313460, 2025). "The gingipain virulence factors of P. gingivalis promote cell proliferation, inhibit apoptosis, and accelerate inflammatory responses by regulating the PI3K/AKT and MAPK signaling pathways, which are also involved in TIMP1-mediated colon cancer progression and metastasis." (PMID 40313460, 2025). "Song28 found that the FAK-PI3K/AKT and MAPK pathways may be signaling pathways involved in the inhibition of colon cancer cell proliferation, migration, and invasion by TIMP1." (PMID 38167930, 2024).
colon carcinoma (continued). "Hence, we used the TIMER database to analyze the correlation between CCL3, MMP3, and TIMP1 expression and immune cell infiltration status in patients with colon cancer." (PMID 36742294, 2023). "And TIMP1 could be an independent prognostic biomarker of OS and disease-free survival for colon cancer patients." (PMID 37056778, 2023). "TIMP1 is a natural inhibitor of matrix metalloproteinases, and the imbalance between TIMP1 and matrix metalloproteinases in gastrointestinal cancers is a crucial element in colon cancer." (PMID 36816016, 2023). "In addition, CCL3, MMP3, and TIMP1 expression were negatively correlated with tumor purity in colon cancer (P = 2.30e-8, cor = -0.273; P = 6.68e-5, cor = -0.196 and P = 7.41e-16, cor = -0.385, respectively)." (PMID 36742294, 2023). "Therefore, we next analyzed if there was a correlation between the expression of hub genes such as CCL3, MMP3, and TIMP1 and infiltrating immune cells in colon cancer." (PMID 36742294, 2023). "The expression of TIMP-1 in the plasma and tissues of patients with cancer is highly increased, with more significant levels related to worse clinical results in various cancers, including prostate and colon cancers." (PMID 34208730, 2021). "TIMP-1 has been identified as a target of aberrant N-glycosylation by the action of N-acetylglucosaminyltransferase V in human WiDr colon cancer cells, and this aberrant TIMP-1 glycoform has been associated with tumor cell invasion in vitro and metastasis in vivo." (PMID 34502227, 2021). "In colon cancer, TIMP1 has higher expression levels in tumor tissues and lymph node metastases than in normal tissues, the expression level of TIMP1 in colon cancer is significantly positively correlated with CD4+T cells, macrophages, neutrophils and dendritic cells." (PMID 34552622, 2021). "Finally, the ARGPI was constructed based on five apoptosis genes (FAS, VWA5A, SPTBN2, PCK1, and TIMP1), which can effectively improve the prediction of colon cancer progression." (PMID 34957118, 2021). "TIMP1 can act as a potential prognostic indicator for colon cancer." (PMID 34790823, 2021). "The role of aberrant TIMP-1 N-glycosylation was later confirmed with the study that showed that these colon cancer cells transfected with an aglycosylated TIMP-1 mutant show a lower rate of cell proliferation, less resistance to apoptosis, and retarded tumor growth." (PMID 34502227, 2021). "Moreover, recent studies have found that TIMP1 is an independent prognostic indicator for disease-free survival and OS in colon cancer patients through the Cox proportional hazards model." (PMID 32127941, 2020). "In addition, increased PCK activity induced by phorbol-12-myristate-13-acetate (PMA) augments TIMP1 expression in colon cancer cells." (PMID 28430130, 2017). "However, the significance of TIMP1 and its mechanism of action in the progression of colon cancer have been rarely reported." (PMID 27644693, 2016). "TIMP1 might play an important role in promoting tumorigenesis and metastasis of human colon cancer and function as a potential prognostic indicator for colon cancer." (PMID 27644693, 2016). "In summary, the present study identified that TIMP1 is overexpressed in colon tumor samples and that dysregulated TIMP1 expression, which occurs frequently in colon cancer, leads to tumor proliferation, metastasis and anti-apoptosis by FAK-PI3K/AKT and MAPK pathway." (PMID 27644693, 2016). "In the present study, our experiments showed that depletion of TIMP1 could suppress colon cancer cell proliferation, migration and invasion in vitro, and suppress the tumorigenicity and metastasis of colon cells in vivo." (PMID 27644693, 2016). "However, further explorations are needed to fully elucidate the molecular mechanisms governing TIMP1 gene dysregulation and its role in colon cancer progression." (PMID 27644693, 2016).
colon carcinoma (continued). "Cox proportional hazards model showed that TIMP1 was an independent prognostic indicator of disease-free survival (HR = 2.603, 95 % CI: 1.115–6.077, p = 0.027) and overall survival (HR = 2.907, 95 % CI: 1.254–6.737, p = 0.013) for patients with colon cancer." (PMID 27644693, 2016). "A role and implication of expressions of MMP-7, COX-2 and TIMP-1 in colon cancer is predicted." (PMID 29201696, 2015). "We showed that TIMP-1 promotes progression of prostate and colon cancer." (PMID 24143225, 2013). "We then assessed the effect of TIMP-1 on colon cancer growth in vivo." (PMID 24143225, 2013). "In addition, the change of ferroptosis index showed that PMFs promoted the occurrence of ferroptosis, followed by Q-PCR and WB detection of NOX4 and TIMP1, the key genes screened by bioinformatics, found that PMFs inhibited PD-L1 by down-regulating TIMP1, thus affecting colon cancer." (PMID 40290432, 2025). "Moreover, this study also found that TIMP1, as a membrane tension-related gene, may serve as a therapeutic target in colon cancer patients." (PMID 36146640, 2022). "TIMP-1 may serve as a prognostic indicator for progression and metastasis in colon cancer." (PMID 31829287, 2019). "In addition, TIMP1 could also increase anti-apoptosis of colon cancer in BAD mediated phosphoration pathway." (PMID 27644693, 2016). "We found that TIMP-1 level is elevated in the stroma of colon cancer comparing to that of normal colon and that stroma of undifferentiated/higher grade colon cancer and metastatic colon cancers displayed higher levels of TIMP-1 comparing to stroma of differentiated/lower grade colon cancer." (PMID 24143225, 2013). "TIMP1 can accelerate tumor progression and metastasis by regulating the FAK-PI3K/AKT and MAPK pathways in colon cancer." (PMID 39247594, 2024). "Through qRT-PCR testing, we observed that in colon cancer tissue, the mRNA expression levels of VEGFA (p < 0.05), TIMP1 (p < 0.0001), MYC (p < 0.0001), and EPHA2 (p < 0.05) were higher than in normal tissue." (PMID 38773226, 2024). "Before we started, we detected the expression levels of MMP3, MMP9, TIMP1, VEGFA in various colon cancer cell lines by qRT-PCR assay, and found that these genes were highly expressed in RKO and SW480, and we chose RKO and SW480 for the following experiments." (PMID 39177661, 2024). "TIMP-1 has been reported to activate both the PI3K/AKT and MAPK signaling pathways via its metalloprotease inhibitor function in the context of breast and colon cancer." (PMID 37508563, 2023). "The results revealed that CCL3, MMP3, and TIMP1 expression was positively correlated with the infiltration status of immune cells like DCs, CD8+ T cells, and neutrophils in colon cancer." (PMID 36742294, 2023). "The results of the cell showed that the down-regulation of TIMP-1 inhibited the migration, invasion and metastasis of LUAD cells; While the high level of TIMP-1 in serum or plasma of colon cancer patients is negatively related to the survival of patients." (PMID 36690987, 2023). "To examine the consequences of higher extracellular TIMP-1 concentrations for AnD5 cells, we first performed experiments with PMA, which has previously been demonstrated to increase TIMP-1 secretion by colon cancer cells." (PMID 36291767, 2022). "Song revealed that TIMP1 promoted tumor progression and suppressed apoptosis via FAK-PI3K/AKT and MAPK pathway in colon cancer." (PMID 35281807, 2022).